EREG (epiregulin)
Diseases named in the same sentence as EREG in open-access papers (continued):
Sharing a sentence is not in itself a finding about the gene and the disease.
glioma (10 papers, 2013 to 2025). A benign or malignant brain and spinal cord tumor that arises from glial cells (astrocytes, oligodendrocytes, ependymal cells). "The loss of FTO in aggressive glioma would therefore lead to the stabilization and accumulation of EREG mRNA, fueling a proliferative signaling cascade." (PMID 40970086, 2025). "Indeed, EREG expression is higher in high- compared to low-grade glioma and loss of EREG correlates with increased survival." (PMID 38514807, 2024). "Our investigation into the underlying mechanism led us to identify EREG as a novel and critical downstream target of FTO in glioma." (PMID 40970086, 2025). "Treatment with cetuximab inhibited the EREG-mediated cell proliferation of glioma cells with abundant EREG expression." (PMID 38398101, 2024). "In our study, we detected EREG mRNA expression and protein levels in tissues and multiple glioma cell lines." (PMID 36647156, 2023). "To further evaluate the expression of EREG and Rab27b in glioma cell lines, we analyzed the protein levels in the H4 (neuroglioma), SW1088 (astrocytoma), A172 (GBM), U118MG (GBM), and U87MG (GBM) cells." (PMID 33409495, 2020). "In this work, EREG expression analyses were performed in several glioma cell lines and were also inventoried in high-grade gliomas from the GEO and Oncomine databases." (PMID 24330607, 2013). "We then evaluated the clinical significance of EREG expression in human gliomas, of which a significant percentage accumulates high levels of ErbB proteins." (PMID 24330607, 2013). "Here we considered the possible implication of the EGFR ligand epiregulin (EREG) in glioma development in relation to the activity of the unfolded protein response (UPR) sensor IRE1α." (PMID 24330607, 2013). "The relationship identified between IRE1α invalidation and the decrease in EREG mRNA level was further monitored in U87 glioma cells incubated with tunicamycin, an antibiotic that inhibits N-linked protein glycosylation and triggers ER-stress." (PMID 24330607, 2013). "The reasons underlying these modulations likely reflect the wide heterogeneity of gliomas and the possible intervention of a set of transcription factors involved in EREG expression and tumor progression." (PMID 24330607, 2013). "Cross-talk between the EREG and VEGFA ligands in the tumor microenvironment has also been found in a single cell transcriptome analysis uncovering that EREG mediates cuproptosis in glioma cells, where high cuproptosis activation scores were significantly enriched in VEGFA + malignant cells." (PMID 38398101, 2024). "Additionally, we found that the protein expression levels of EREG in glioma cell lines were higher than that in normal astrocytic cell lines." (PMID 36647156, 2023). "The EREG mRNA expression levels were high in tissues and multiple glioma cell lines." (PMID 36647156, 2023). "EREG mRNA and protein levels were monitored in several human glioma cell lines." (PMID 24330607, 2013). "EREG may contribute to glioma progression under the control of IRE1α, as exemplified here by the autocrine proliferation loop mediated in U87 cells by the growth factor through ErbB1." (PMID 24330607, 2013). "Besides, the autocrine contribution of EREG is likely to be reduced in the U87 glioma model, as these fast-growing tumors secrete other growth-promoting and angiogenic polypeptides and may exploit alternative signaling pathways for expansion." (PMID 24330607, 2013). "Microarray analyses of gliomas at different grades of malignancy indicated that EREG transcripts were detected in highly variable amounts in tumor tissues, although no clear relationship was established between EREG mRNA levels and the glioma grade or brain tumor type." (PMID 24330607, 2013). "In summary, our study delineates a clear tumor-suppressive pathway in glioma: FTO demethylates and destabilizes EREG mRNA, which limits EREG-mediated activation of the PI3K/Akt pathway." (PMID 40970086, 2025).
glioma (continued). "Our findings demonstrate that FTO suppresses glioma proliferation and cell cycle progression by regulating the stability of Epiregulin (EREG) mRNA and subsequently inactivating the PI3K/Akt signaling pathway, thereby establishing its role as a key tumor suppressor in glioma." (PMID 40970086, 2025). "Interestingly, the co-upregulation of Rab27b and epiregulin (EREG), a member of the epidermal growth factor (EGF) family, correlated with radioresistance in glioma cell lines." (PMID 33409495, 2020). "Furthermore, Rab27b regulates the expression of EREG and further participates in paracrine signaling by activating EGF receptor (EGFR) in different types of glioma cells after IR treatment." (PMID 33409495, 2020). "However, the possible implication of EREG in glioma development has not yet been addressed, even though the pathological significance of EGFR has been well established in this pathology." (PMID 24330607, 2013).
pancreatic cancer (10 papers, 2005 to 2024). "The results of gene screening demonstrated that EREG was associated with the prognosis of pancreatic cancer, so our approach could be used to accurately screen prognostic genes." (PMID 32596278, 2020). "Previous studies revealed that EREG is upregulated in pancreatic cancer and stimulates the growth of pancreatic cancer cells." (PMID 32596278, 2020). "To determine if enhancer activity is required for AREG and EREG expression in pancreatic cancer cells, we treated cells with JQ1, a BET bromo-domain inhibitor that is specific for BRD432." (PMID 28733611, 2017). "Interestingly, high integrin α6β4 in pancreatic cancer cells is associated with transcriptional upregulation of EGFR ligands, including EREG, which activates EGFR signalling and enhances cell motility and migration." (PMID 38687323, 2024). "We modulated GADD45A in pancreatic cancer cells using either siRNA to knockdown or adenoviral infection to overexpress GADD45A and examined the effects on AREG and EREG expression." (PMID 28733611, 2017). "Pancreatic cancer cells over express EGF, along with other members of the EGF family such as Cripto and epiregulin." (PMID 15801978, 2005). "EREG is up-regulated in PDAC and stimulates pancreatic cancer cell growth in vitro." (PMID 33748108, 2021). "Integrin α6β4 is highly expressed in pancreatic carcinoma and contributes to cancer progression, in part, through the specific DNA demethylation and upregulation of epidermal growth factor receptor (EGFR) ligands amphiregulin (AREG) and epiregulin (EREG)." (PMID 28733611, 2017).
head and neck squamous cell carcinoma (9 papers, 2016 to 2025). A squamous cell carcinoma that arises from any of the following anatomic sites: lip and oral cavity, nasal cavity, paranasal sinuses, pharynx, larynx, and salivary glands. "EREG is also involved in the progression of head and neck squamous cell carcinomas, where its loss has been suggested as a predictive biomarker for patients that might benefit from a combination of ferroptosis inducers and cetuximab." (PMID 39654143, 2024). "Oligosaccharyltransferase subunit (STT3B) was shown to stabilize Epiregulin via N-glycosylation, which is crucial for PD-L1 upregulation and immune escape in head and neck squamous cell carcinoma." (PMID 40519935, 2025). "In head and neck squamous cell carcinoma, EREG enhances malignant transformation by activating the MAPK pathway and inducing C-Myc expression." (PMID 37020674, 2023). "Drug sensitivity to the SHP inhibitor SHP099 for head and neck squamous cell carcinoma (HNSCC) is dependent on EREG." (PMID 38398101, 2024). "Dysregulated Epiregulin (EREG) can activate epidermal growth factor receptor (EGFR) and promote tumor progression in head and neck squamous cell carcinoma (HNSCC)." (PMID 38945975, 2024).
non-small cell lung carcinoma (9 papers, 2020 to 2025). A group of at least three distinct histological types of lung cancer, including non-small cell squamous cell carcinoma, adenocarcinoma, and large cell carcinoma. "For instance, EREG has been shown to promote resistance to targeted therapies in non-small cell lung cancer." (PMID 39744439, 2025). "Increasing evidence indicates that both the aberrant expression and oncogenic function of EREG play pivotal roles in tumor development in many human cancers, including non-small cell lung cancer (NSCLC)." (PMID 38398101, 2024). "Deregulated EREG activity contributes to the progression of a variety of malignancies, including non-small-cell lung cancer." (PMID 32587640, 2020). "It is becoming evident that EREG contributes to the epithelial–mesenchymal transition, cancer stemness, immune evasion, and resistance to anticancer drugs in several human cancers, including non-small cell lung cancer." (PMID 38398101, 2024). "Overexpression of EREG, GTPBP2, and DRG2 was linked to tumor growth in non-small cell lung cancer." (PMID 36809921, 2023).
bladder cancer (8 papers, 2015 to 2024). "EREG is overexpressed in bladder cancer, which leads to a high risk of lung metastasis." (PMID 34884633, 2021). "In a COX2-overexpressed bladder cancer model, EREG is identified as the most highly expressed EGF, supporting tumor cell proliferation." (PMID 37020674, 2023). "Deregulated EREG activity appears to contribute to the progression of a number of different malignancies, including cancers of the bladder, stomach, colon, breast, lung, head and neck, and liver." (PMID 36647156, 2023). "In a COX2-overexpression mouse model, EREG was the most highly expressed growth factor in bladder carcinoma and promoted cancer cell proliferation." (PMID 34884633, 2021). "An inverse correlation was observed between EREG gene expression and DNA methylation in other cancers, including head and neck, lung, and bladder cancer." (PMID 34884633, 2021). "In bladder cancer, EREG expression was increased in patients with the advanced disease stage, and high EREG mRNA expression was substantially associated with poor survival outcomes." (PMID 34884633, 2021). "Altered expression of EGF family members (e.g. EGF, epiregulin and HB-EGF (heparin-binding epidermal growth factor-like growth factor)) and EGFR has been suggested as mediators of bladder cancer progression." (PMID 26250800, 2015).
metastatic colorectal cancer (8 papers, 2011 to 2023). "Using clinical data and a meta-analysis, high AREG and EREG mRNA expression levels were found to be associated with both progression-free and overall survival of patients with metastatic colorectal cancer treated with Cetuximab-based chemotherapy." (PMID 31181806, 2019). "More recently, an elevated level of epiregulin was found to be associated with a greater benefit from cetuximab therapy, demonstrating the predictive role of EREG expression in the context of anti-EGFR therapeutic efficacy in metastatic colorectal cancer." (PMID 32929368, 2020). "Epiregulin expression has also been shown to be a predictive biomarker of response to anti-EGFR therapies in metastatic colorectal cancer." (PMID 31181806, 2019). "We conducted a meta-analysis of studies that investigated AREG and/or EREG mRNA levels in primary tumors to determine their prognostic value in metastatic colorectal cancer (mCRC)." (PMID 27344184, 2016). "A phase III trial demonstrated that EREG expression can be a predictor for overall survival in oxaliplatin/fluoropyrimidine plus bevacizumab-treated metastatic colorectal cancer patients without RAS and BRAF mutations." (PMID 32587640, 2020). "In terms of EREG/AREG as a combined dichotomous biomarker, data from the PICCOLO trial confirmed that high ligand mRNA levels or IHC positivity are predictive biomarkers of benefit from panitumumab treatment in patients with metastatic colorectal cancer." (PMID 37974093, 2023).
prostate carcinoma (8 papers, 2009 to 2024). A carcinoma that arises from epithelial cells of the prostate gland. "The results demonstrate epiregulin regulation by different mechanism and suggest a potential role as a diagnostic tool to detect molecular alterations in prostate cancer progression." (PMID 36994208, 2023). "This anti-EREG antibody also enhanced the tumor-suppressive effect of the anti-cancer agent mitoxantrone in a xenograft model composed of prostate cancer cells and EREG-overexpressing prostate stromal cells." (PMID 38398101, 2024). "Five different prostate carcinoma cell lines were used to characterize the epiregulin expression on the RNA and protein levels." (PMID 36994208, 2023). "Epiregulin expression and its correlation with different patient conditions were further analyzed using clinical prostate cancer tissue samples." (PMID 36994208, 2023). "An increased epiregulin secretion is detected in castration-resistant prostate cancer cell lines and prostate cancer tissue samples indicating a correlation of epiregulin expression with tumor recurrence, metastasis and increased grading." (PMID 36994208, 2023). "In summary, the results suggest enhanced expression of EREG in advanced metastatic prostate carcinomas." (PMID 36994208, 2023). "This study aims to reveal the expression and regulation of epiregulin in different prostate cancer stages enabling a more specific molecular characterization of different prostate carcinoma types." (PMID 36994208, 2023). "The pro-oncogenic activities of AREG and EREG have been examined in previous studies of lung, breast, colorectal, and prostate carcinoma." (PMID 32674321, 2020). "Markedly, our data demonstrate that the activated EGFR signaling-induced autocrine AREG, EREG, and TGFA expression in Ras-mutated prostate cancer cells is associated with a down-regulation in miR-203 expression level in an EGF-dependent manner." (PMID 25004126, 2014). "Although Ereg expression is highly correlated with survival from bladder cancer, others suggest epiregulin to be important for pancreatic and prostate cancer development." (PMID 19529782, 2009). "Given the critical role of Ras mutation-induced EGFR signaling activation in prostate cancer progression, we hypothesized that EGF-induced autocrine AREG, EREG, and TGFA expression might be directly mediated by miR-203 in RasB1 cells." (PMID 25004126, 2014). "Additionally, although EGFR inhibitors false in prostate cancer, epiregulin could be a therapeutic target for patients with castration-resistant prostate cancer." (PMID 36994208, 2023). "The release of mature epiregulin occurs via proteolytic cleavage by ADAM17, MMP2, and MMP9 which are increased in castration-resistant prostate cancer cells." (PMID 36994208, 2023). "The results from the analysis of clinical specimens suggest that decreasing miR-203 and increasing of EGFR ligands, (EREG and TGFA) expression are correlated with prostate cancer progression." (PMID 25004126, 2014). "In prostate cancer patients, our data showed that miR-203 levels were inversely correlated with the expression of two EGFR ligands, EREG and TGFA, and an EGFR dependent gene signature." (PMID 25004126, 2014). "Moreover, we observed a high expression of AREG, EREG, and TGFA in tumors that had higher KRAS oncogenic response gene signatures in the human prostate cancer dataset." (PMID 25004126, 2014).
cervical cancer (7 papers, 2021 to 2024). A primary or metastatic malignant neoplasm involving the cervix. "The second candidate, EREG (epiregulin), is a risk factor for the prognosis and a potential target for drug development of patients with cervical cancer." (PMID 39654143, 2024). "In the present study, we found that high EREG expression was associated with the poor survival of patients with cervical cancer." (PMID 37020674, 2023). "The findings revealed that EREG overexpression was associated with a poor prognosis in patients with cervical cancer." (PMID 37020674, 2023). "EREG would be a promising target for risk classification and drug development for patients with cervical cancer." (PMID 37020674, 2023). "A pan-cancer survival analysis of cancer hallmark genes in cervical cancer indicated that EREG can cause replicative immortality." (PMID 34884633, 2021). "Survival analysis showed that EREG was a risk factor for the prognosis of cervical cancer." (PMID 37020674, 2023). "In this study, we calculated the correlations between EREG expression and clinical-pathological characteristics and prognosis of patients with cervical cancer." (PMID 37020674, 2023). "Collectively, high EREG expression predicts poor prognostic outcomes for patients with cervical cancer." (PMID 37020674, 2023). "EREG plays a vital role in the progression of cervical cancer, which contributes to hyperactive cell proliferation and decreased cell apoptosis." (PMID 37020674, 2023). "In conclusion, our data showed that EREG functioned as a driving factor in cervical cancer progression and contributed to chemotherapy resistance." (PMID 37020674, 2023). "The results verified the putative EREG pathway and indicated the cervical cancer cells would trend to apoptosis when the EREG declined." (PMID 37020674, 2023). "Based on the public database, we found that the expression of EREG was higher in advanced cervical cancer samples." (PMID 37020674, 2023). "In this study, we first conducted a comprehensive biological analysis to investigate the expression of EREG in cervical cancer." (PMID 37020674, 2023). "EREG is down-regulated in cervical cancer; because of its critical function, EREG is a good candidate for anticancer therapy." (PMID 34439555, 2021). "The proliferation assay using CCK8 showed that the knockdown of EREG could impede cervical cancer cell proliferation." (PMID 37020674, 2023). "Moreover, we measured the effects of EREG knockdown on the proliferation and apoptosis of cervical cancer cells." (PMID 37020674, 2023). "In addition, we validated the effects of EREG expression on the proliferation and apoptosis of cervical cancer cells." (PMID 37020674, 2023). "Since EREG downregulation could trigger cervical cancer apoptosis, it is logical that declining EREG could be a promising therapy for cervical cancer." (PMID 37020674, 2023). "In conclusion, it is logical that targeting EREG could be a potential strategy for cervical cancer treatment." (PMID 37020674, 2023). "Therefore, it is apparent to detect the proliferation of cervical cancer with different EREG expression statuses." (PMID 37020674, 2023). "Therefore, the apoptosis analysis was undertaken to detect the apoptosis rate of cervical cancer cells with different EREG expression levels." (PMID 37020674, 2023). "Collectively, we showed that EREG might be a promising prediction biomarker and treatment target for cervical cancer in the future." (PMID 37020674, 2023). "Furthermore, we investigated the relationship between the EREG expression condition of patients with cervical cancer and clinical significance, including stage status and T status." (PMID 37020674, 2023). "Therefore, to further explore the effect variation of cisplatin on cervical cancer cells as the expression of EREG is downregulated, the CCK8 cell viability assay was conducted." (PMID 37020674, 2023). "EREG knockdown impairs proliferation and promotes apoptosis of cervical cancer cells." (PMID 37020674, 2023).